RPL10 (ribosomal protein L10)
Diseases named in the same sentence as RPL10 in open-access papers (continued):
Sharing a sentence is not in itself a finding about the gene and the disease.
leukemia (5 papers, 2019 to 2023). A malignant (clonal) hematologic disorder, involving hematopoietic stem cells and characterized by the presence of primitive or atypical myeloid or lymphoid cells in the bone marrow and the blood. "Noteworthy, point mutations in RPs contribute to development of leukemia, such as R98S in RPL10 in T cell ALL." (PMID 37123244, 2023). "While the contribution of R98S RPL10 mutation to pediatric T-ALL has been extensively studied, nothing is known about the contribution to leukemia of other RPL10 mutations, like the ones involving Q123." (PMID 36482893, 2022). "For example, the leukemia-associated R98S mutation in RPL10 (uL16) drives specific and constitutive IRES-mediated overexpression of the anti-apoptotic factor BCL-2." (PMID 30862070, 2019). "In this regard, a proof-of-concept was recently presented in the context of the leukemia-associated RPL10-R98S (uL16-R98S) mutation." (PMID 30862070, 2019). "The proteome changes induced by the leukemia-associated RPL10-R98S (uL16-R98S) mutation were shown to mainly belong to metabolism pathways." (PMID 30862070, 2019). "In the case of the leukemia associated RPL10-R98S (uL16-R98S) mutation, enhanced levels of ROS may arise from increased peroxisome activity." (PMID 30862070, 2019). "Exome sequencing and other approaches have further shown that mutations in RPL5 (uL18), RPL10 (uL16), RPL11 (uL5), RPL22 (eL22), RPS15 (uS19) and RPS20 (uS10) are present in a variety of cancers, especially leukaemia." (PMID 37526268, 2023). "As a consequence, leukemias carrying the RPL10-R98S (uL16-R98S) defect are highly sensitive to the clinically used BCL-2 inhibitor Venetoclax." (PMID 30862070, 2019).
multiple myeloma (5 papers, 2019 to 2025). "As far as the first are concerned, three RPL10 mutations have been described with low frequency (2%) in multiple myeloma." (PMID 33227977, 2020).
autism spectrum disorder (4 papers, 2009 to 2023). A spectrum of developmental disorders that includes autism, and Asperger syndrome. "In particular, mutations in rpS23 and rpL10 have been shown to be associated with autism spectrum disorder, a disorder that has been associated with aberrant 5-HT function." (PMID 36048889, 2022). "RPL10 mutations have been linked to autism spectrum disorder (ASD) mechanisms." (PMID 33414392, 2021).
prostate carcinoma (4 papers, 2009 to 2023). A carcinoma that arises from epithelial cells of the prostate gland. "In prostate cancer patients, reduced expression of RPL10 has been suggested to associate with early development of the cancer; however, high expression of RPL10 at later stages of cancer development could drive forward to a more aggressive phenotype." (PMID 28388532, 2017). "In prostate cancer, the expression of RPL10 is gradually increased with the progress of the disease." (PMID 37280198, 2023). "In early developmental stage of prostate cancer, RPL10 level was decreased, and higher level of RPL10 could promote tumor deterioration at late stage." (PMID 30172100, 2018).
Intellectual disability (3 papers, 2021 to 2022). "Most of these sequence variations turned out to be germline alterations, with no known pathogenetic effect, except for p.S202N (c.G605A) in RPL10, which had previously been associated with intellectual disability." (PMID 36482893, 2022).
ovarian carcinoma (3 papers, 2016 to 2023). A malignant neoplasm originating from the surface ovarian epithelium. "Regarding the relationship with cancer, RPL10 has been implicated as a biomarker and target for human epithelial ovarian cancer." (PMID 37280198, 2023).
pancreatic adenocarcinoma (3 papers, 2023 to 2024). "Another group identified that the UFMylation of RPL10 (ribosomal protein L10) contributed to pancreatic adenocarcinoma development." (PMID 39247188, 2024). "Another ribosomal protein RPL10, a regulator of actively translating ribosome formation, is reportedly UFMylated to significantly increase cell proliferation in pancreatic adenocarcinoma (PAAD)." (PMID 37947621, 2023).
Wilms tumor (3 papers, 2018 to 2023). An embryonal neoplasm characterized by the presence of epithelial, mesenchymal, and blastema components. "Meanwhile, as a component of 60S subunit and a member of ribosomal proteins, ribosomal protein L10 (RPL10) was first reported in Wilms’ tumor cells." (PMID 37280198, 2023). "On the other hand, when compared with Wilms’ tumor and clear cell sarcoma of the kidney, RPL5 and RPL10 were signifcantly downregulated in KRT." (PMID 30479569, 2018). "Human ribosomal protein L10 (RPL10), also known as QM, is a 25 kDa basic protein first found in nontumorigenic Wilms’ tumor, participating in the late steps of 60 S ribosome assembly." (PMID 30172100, 2018).
colorectal cancer (2 papers, 2018 to 2025). A primary or metastatic malignant neoplasm that affects the colon or rectum. "Mutations in RPL10 and RPL22 have also been implicated in tumorigenesis and identified in additional cancer types, including the rare somatic RPL10 mutations in MM and RPL22 mutations producing truncated proteins in endometrial, gastric and colorectal cancer samples." (PMID 40805230, 2025).
melanoma (2 papers, 2021 to 2025). A malignant, usually aggressive tumor composed of atypical, neoplastic melanocytes. "BRAF V600K melanomas were downregulated for module 1 (RPS15, RPL29, RPL10)." (PMID 39796775, 2025).
Alzheimer disease (1 paper, 2020). A progressive, neurodegenerative disease characterized by loss of function and death of nerve cells in several areas of the brain leading to loss of cognitive function such as memory and language. "In a study on Alzheimer’s disease (AD), RPL10 was shown to be involved in cell death regulation, taking part in the signaling cascade induced by Presenilin 1 (PS1), which is a causative gene for an autosomal dominant familial AD." (PMID 33227977, 2020).
asthma (1 paper, 2023). "State 1 was defined as asthma-related eosinophils predominantly found in the asthma model, including the following genes: H2Aa, Ms4a2, Fcer1g, and Rpl10." (PMID 37816708, 2023).
COVID-19 (1 paper, 2023). A disease caused by infection with severe acute respiratory syndrome coronavirus 2. "Some recent papers have provided evidence of altered RPL10 gene expression after COVID-19 vaccination." (PMID 36936955, 2023). "COVID-19 vaccination produces a large number of antibodies, and based on the previously postulated contribution of the RPL10 gene to antibody production by B cells, RPL10 expression may be altered after vaccination." (PMID 36936955, 2023). "Although no subsequent literature has demonstrated COVID-19 vaccination-induced differential expression of RPL10, RPS3, and RPS4X in CD4+ T cells, these genes are still considered potent features." (PMID 36936955, 2023).
cystic teratoma (1 paper, 2024). "In summary, amplifications of EVX2, HOXD13, HOXD12, HOXD11, HOXD10, and HOXD9 on 2q31.1, NDUFV1 on 11q13.2, and RPL10, SNORA70, DNASE1L1, TAZ, ATP6AP1, and GDI1 on Xq28 were found in all nine mature cystic teratomas in this study." (PMID 38907278, 2024). "Amplifications and deletions of large DNA fragments were observed in some samples, while amplifications of EVX2 and HOXD9-HOXD13 on 2q31.1, NDUFV1 on 11q13.2, and RPL10, SNORA70, DNASE1L1, TAZ, ATP6AP1, and GDI1 on Xq28 were found in all nine mature cystic teratomas." (PMID 38907278, 2024).
Infertility (1 paper, 2023). "The topological analysis of the WGCN of the testis transcriptional cell atlas highlighted important somatic genes in this network, including RPL39, RPL10, RPL13A, FTH1, RPS2, and RPL18A, which have been reported to be associated with infertility." (PMID 38012716, 2023).
male infertility (1 paper, 2023). The inability of the male to effect fertilization of an ovum after a specified period of unprotected intercourse. "We also identified key somatic cell genes, including RPL39, RPL10, RPL13A, FTH1, RPS2, and RPL18A, which were highly influential in the weighted gene co-expression network of the testis transcriptional cell atlas and have been previously implicated in male infertility." (PMID 38012716, 2023).
medulloblastoma (1 paper, 2018). A malignant, invasive embryonal neoplasm arising from the cerebellum. "After comparison with other common pediatric tumors, RPL5 and RPL10 can also be used to distinguish AT/RT from medulloblastoma." (PMID 30479569, 2018). "Compared with medulloblastoma, RPL5 and RPL10 were signifcantly upregulated in AT/RT, with fold changes of 1.25 and 1.5 (p < 0.001), respectively." (PMID 30479569, 2018).
Parkinson disease (1 paper, 2025). A progressive degenerative disorder of the central nervous system characterized by loss of dopamine producing neurons in the substantia nigra and the presence of Lewy bodies in the substantia nigra and locus coeruleus. "For example, using AskBeacon, clinicians and researchers can validate in their data whether the genetically determined sex differences in Parkinson's Disease (Klein and König 2021) are due to X-linked [RPL10] or autosomal [SNCA] genetic factors." (PMID 39985504, 2025).
pediatric tumors (1 paper, 2018). "Together, these results suggest that RPL5 and RPL10 as promising diagnostic markers not only in distinguishing for AT/RT from normal tissues but also in from other types of pediatric tumors." (PMID 30479569, 2018).
rhabdoid tumor (1 paper, 2018). An aggressive malignant embryonal neoplasm usually occurring during childhood. "Our study mined existing GEO datasets for novel diagnostic markers associated with Rhabdoid tumors, and identified RPL5 and RPL10 as potential diagnostic markers for AT/RT." (PMID 30479569, 2018).
Sepsis (1 paper, 2025). Sepsis is defined as life-threatening organ dysfunction caused by a dysregulated host response to infection. "Key genes we identified, such as RPL10, MYL12B, and PPIA, have been shown to play significant roles in the mechanisms associated with sepsis and AKI." (PMID 40428155, 2025).
T-cell leukemia (1 paper, 2017). A malignant disease of the T-lymphocytes in the bone marrow, thymus, and/or blood. "Ribosomes containing mutations in Rpl10 associated with pediatric T-cell leukemia fail in this quality control check and prevent the removal of Tif6 and Nmd3." (PMID 28715419, 2017).
TKCR syndrome (1 paper, 2006). "Due to its expression pattern, and taking imprecise linkage analysis into consideration, RPL10 is a good candidate for TKCR syndrome." (PMID 16503986, 2006).
X-linked dyskeratosis congenita (1 paper, 2015). "The idea that perturbations in ribosome structure may deregulate translation of mRNAs encoding cancer-promoting proteins is supported by published data, as illustrated by X-linked dyskeratosis congenita or from research performed on single mutated genes coding for RPs, as RPL38 or RPL10." (PMID 25886394, 2015).
X-linked intellectual disabilities (1 paper, 2023). "Ribosomopathic mutations in uL16/RPL10 cause X-linked intellectual disabilities." (PMID 37047306, 2023).
X-linked recessive syndromic intellectual developmental disorder-35 (1 paper, 2025). "Disease-causing RPL10 variants have been found to be responsible for X-linked recessive syndromic intellectual developmental disorder-35 (MRXS35; OMIM#300998)." (PMID 40861044, 2025).
cancer (26 papers, 2016 to 2026). A tumor composed of atypical neoplastic, often pleomorphic cells that invade other tissues. "R98S RPL10 mutation has been extensively studied for its impact on ribosome and for its role in cancer onset." (PMID 33227977, 2020). "Even though most of the scientific literature about RPL10 alterations in cancer is related to T-ALL, this RP has been linked to other hematological and solid tumors." (PMID 33227977, 2020). "More importantly, mutations in RPL10 gene have been recently detected in cancer patients who are unrelated to any heritable diseases." (PMID 28388532, 2017). "Despite the association between RPL10 expression and cancer development in the literatures, whether post-translational modifications of RPL10 plays a role in cancer development remains poorly understood." (PMID 37280198, 2023). "In this sense, RPL10 mutations seem to slow down the rush of cancer cells toward uncontrolled growth, metabolism, and accumulation of toxic products, which could become unbearable in the long run." (PMID 33227977, 2020). "In this sense, it is possible that RPL10 mutations may provide a protective effect for cancer cells." (PMID 33227977, 2020). "For instance, the T-ALL-associated ul16/RPL10-R98S mutation triggers profound structural, biochemical, and translational fidelity defects that may drive cancer evolution through gene expression reprogramming." (PMID 29674660, 2018). "It would be interesting to explore whether resistance to oxidative stress driven by this pool of ribosomes is also present in other cancers as well as evaluate whether acquisition of mutations in Rpl10 could be a possible resistance approach adopted by cancer cells during tumor development." (PMID 38989007, 2024). "Recurrent mutations in genes of the large 60S subunit components RPL5, RPL10, RPL11, RPL22, and RPL23A, and the small 40S subunit components RPS15, RPS20, and RPS27 have been specifically implicated in cancer." (PMID 40805230, 2025). "RPL10 UFMylation enhances cell proliferation and promoted cancer cell stemness, primarily through upregulated expression of KLF4 (kruppel-like transcription factor 4)." (PMID 39247188, 2024). "RPL10 UFMylation enhances cell proliferation and promoted cancer cell stemness via upregulation of KLF4." (PMID 39247188, 2024). "For the data set of OV, 67 genes were identified by univariate Cox regression to be significantly associated with the cancer and seven of them, namely COL1A1, COL3A1, RPL10, ARHGAP5, LATS1, TSHR and SLC34A2, were found in the CGC data set." (PMID 32429941, 2020). "Here, we reviewed the literature to give an overview of the role of RPL10 in physiologic and pathologic processes, including inherited disease and cancer." (PMID 33227977, 2020). "The present results strongly suggested that the functions of RPL10 in mitochondria are closely related to maintenance of ROS homeostasis in the cells, particularly for cancer cells where a higher level of ROS is usually maintained." (PMID 30172100, 2018). "Nevertheless, although a number of studies have dealt with the molecular basis and functions of RPL10, the actual roles in various types and stages of cancer remain elusive." (PMID 28388532, 2017). "Additionally, oncoribosomes can reprogram cancer metabolism, as seen in T-ALL, where RPL10-R98S mutations induce oxidative stress and deregulated serine/glycine metabolism." (PMID 40805230, 2025). "Mutations in PIK3R1 and RPL10 were not at high prevalence, yet exhibited some of the highest cancer effects in individual T-cell ALL patients." (PMID 38928295, 2024). "RPL10 aids cancer progression by regulating cellular ROS levels in mitochondria." (PMID 35563580, 2022). "This has driven the focus of RPL10 to cancer-related biological events in recent years." (PMID 30172100, 2018). "In summary, this study revealed that RPL10 could enter to mitochondria for the regulation of ROS homeostasis in cancer cells." (PMID 30172100, 2018).
cancer (continued). "Thus, the present results indicated that RPL10 has a close relationship with the energy usage and biological oxidation in cancer cells." (PMID 30172100, 2018). "These phenomena have suggested that extra-ribosomal RPL10 could be an important player in cancer development." (PMID 30172100, 2018). "RPL10 may bind certain mRNA in specific ribosomal protein cistrons and inhibit translation to regulating cancer progression." (PMID 28388532, 2017). "Therefore, even in different tumor types, RPL10 alterations seem to have a common set of consequences on cell behavior and may possibly contribute to cancer onset." (PMID 33227977, 2020). "Thus, it is highly possible that RPL10 may play a buffering role to maintain ROS level within a limited range in cancer cells." (PMID 30172100, 2018). "Two significantly deregulated cancer-related genes, RPL5 and RPL10, showed outstanding performance in the ROC analysis." (PMID 30479569, 2018). "Among the key cancer-related PCGs in the co-expression network, RPL5 and RPL10 showed high levels of sensitivity and specificity AT/RT and KRT." (PMID 30479569, 2018). "Interestingly, LIN28A is associated with specific ribosomal proteins in an RNA-independent mode, and several of these proteins, such as RPL5, RPL10, and RPS27L, have been shown to promote tumorigenesis or cancer." (PMID 34816099, 2021). "Our analyses did not pick up RPL22, RPS27 (eS27), RPS15 and RPL10, although already described in cancer as well." (PMID 28147343, 2017).
tumor (23 papers, 2005 to 2025). "RPL5 and RPL10 are located in sites where decoding takes place inside the ribosome, and exhibit mutations with considerable frequency in tumor cells." (PMID 37958852, 2023). "It is predicted that mutations in ribosomal proteins RPL5 and RPL10 (uL16) are significant drivers in multiple tumour types." (PMID 37526268, 2023). "RPL10 was identified with a mutation that can function as tumor suppressor." (PMID 32498447, 2020). "Then, the difference on RPL10 ufmylation between tumor tissues and adjacent normal tissues from PAAD patients was examined, and higher level of RPL10 ufmylation was found in tumor tissues of PAAD patients." (PMID 37280198, 2023). "When tumor tissues were analyzed, the level of ufmylated RPL10 was markedly decreased from UFL1 knockdown, along with the decline of KLF4." (PMID 37280198, 2023). "Alteration of the expression of ribosomal proteins RPL10 and RPL39 has been linked to tumor initiation and BC progression." (PMID 37922300, 2023). "As a result, the level of RPL10 ufmylation in PAAD tumor tissues was 2-3 fold higher than that in adjacent normal tissues, indicating the close association of RPL10 ufmylation and PAAD development." (PMID 37280198, 2023). "Tumor sizes of UFL1 knockdown were significantly smaller than control group with the decrease of RPL10 ufmylation in tumor tissues." (PMID 37280198, 2023). "Together, the present study suggests that RPL10 could serve as a regulator in mitochondria to balance cellular ROS level during the process of tumor progression." (PMID 30172100, 2018). "In vitro studies have suggested that the protein product of RPL10 may be a tumor suppressor." (PMID 23056603, 2012). "For example, the ribosomal protein L10 (RPL10), also known as QM and DXS648, was firstly identified from human tumor cells as a tumor suppressor." (PMID 34529670, 2021). "For example, alterations in RPs such as RPL5 (uL5), RPL10 (uL16), RPS15 (uS19), RPL11 (uL15), and RPL22 (eL22) have been described in 10–40% of multiple tumor types." (PMID 31590378, 2019). "Our profiles indicate that RARβ2 induces a number of tumor suppressor functions (NDRG1, RPL10, and ST18) and known metastasis suppressors (NDRG1 and TYRP1)." (PMID 16255778, 2005). "Moreover, alterations of RPL5, RPL10, RPS15, RPL11, and RPL22 ribosomal proteins have been described in 10 to 40% of tumor types." (PMID 33462193, 2021). "To evaluate whether RPL5 and RPL10 can be used to distinguish AT/RT and KRT from other tumors, we compared the expression levels of RPL5 and RPL10 in RTs and other types of tumor." (PMID 30479569, 2018).